FBXW7 (F-box and WD repeat domain containing 7)
Diseases named in the same sentence as FBXW7 in open-access papers (continued):
Sharing a sentence is not in itself a finding about the gene and the disease.
tumor (continued). "As an important tumor suppressor by the negative regulation of many oncogenic proteins, FBXW7 is under tight control through various mechanisms, including non-coding RNA, methylation, and other genetic regulation." (PMID 33042830, 2020). "FBXW7 is a ubiquitin ligase and known to function as a tumor suppressor regulating NOTCH, MYC, and other oncogenes." (PMID 30709382, 2019). "Analysis of total protein extracts from tissue specimens evidenced that—despite the high tumor samples heterogeneity—the expression of FBXW7 was significantly induced in the IPA-treated HCT116 xenografts, compared to control tumors." (PMID 31569395, 2019). "An accumulation of pathological data have been proved that FBXW7 is a tumor suppressor by targetting various oncogenic proteins, such as Notch, cyclin E, c-Myc, and c-Jun, for degradation." (PMID 30341246, 2019). "Together with GSK3β, Fbxw7 controls the turnover of a number of key oncogenes such as c-Myc, Cyclin E and NOTCH and has emerged as an important tumour suppressor that is frequently mutated in cancer." (PMID 30854564, 2019). "FBXW7 is considered as a potent tumor suppressor as most of its target substrates can function as potential growth promoters, including c-Myc, Notch, cyclin E, c-JUN, and KLF5." (PMID 30791487, 2019). "In human cancer, F-box and WD-40 domain protein 7 (FBXW7) is member of F-box protein family that acts as classical tumor suppressor." (PMID 31341888, 2019). "It has been well-established that FBXW7 functions as a typical tumor suppressor by targeting a large number of critical human oncoproteins for ubiquitylation and proteasome degradation." (PMID 31342282, 2019). "Conversely, inhibiting the expression of both miR-182 and miR-503 caused up-regulation of FBXW7 in colon cancer AAC1 cells and considerably reduced the tumor size in xenograft models." (PMID 30791487, 2019). "Another oncoprotein, Notch, that has been reported to participate in the development of tumor can also be ubiquitylated by FBXW7 for degradation." (PMID 30791487, 2019). "This happens because efficient degradation of c-Myc requires a protein, which is a tumour suppressor, like FBXW7." (PMID 31068129, 2019). "FBXW7 is a potent tumor suppressor and that can regulate the expression level of many oncoproteins that partake in cellular pathways by directing them for proteasomal degradation thus preventing tumorigenesis." (PMID 30791487, 2019). "It is well-established that FBXW7 acts as a tumor suppressor by promoting the polyubiquitylation via the K48 linkage of a broad range of oncoproteins for proteasome degradation." (PMID 31342282, 2019). "FBXW7 plays an important tumor-suppressive role in regulating the effects of various oncogenic proteins, including cyclin E, c-Myc, c-Jun, Notch, mTOR, and MCL-1." (PMID 30999935, 2019). "FBXW7 has been characterized as a tumor suppressor due to its ability to target several known oncoproteins including MYC, NOTCH, and Cyclin E." (PMID 30647454, 2019). "In fact, FBXW7 is a well-known tumor suppressor that functions as a substrate-recognition protein within a SCF (SKP/CUL1/F-Box) E3 complex ubiquitin ligase complex, which targets numerous proteins for ubiquitin-mediated proteasomal degradation." (PMID 31351478, 2019). "Among all variants, four recurrent substitutions are shared (MAPK1 E322K, PIK3CA E542K and E545K, and FBXW7 R505G) and have similar selection intensities within the two tumor types." (PMID 30647454, 2019).
tumor (continued). "It has been reported that C/EBPδ enhanced mTOR stability by directly inhibiting the expression of FBXW7, resulting in elevation of hypoxia and inflammatory signaling which in turn promoted tumor cell survival." (PMID 30791487, 2019). "We also verified the function of circ-FBXW7 on regulation of tumor growth and the potential target proteins in SW480 and SW620 tumor models." (PMID 31519156, 2019). "Not only do the 2 F-box proteins have different structures and modes of interaction with c-Myc, another important difference lies in the fact that Skp2 is an onco-protein whereas FBXW7 is a tumour suppressor." (PMID 31068129, 2019). "Overall, these studies suggest the potential of FBXW7 as a prognostic marker and its importance as a tumor suppressor for the development of novel and effective therapy for cancer patients." (PMID 30791487, 2019). "In MSI tumours, the most frequently mutated known cancer genes were ACVR2A (9/9, 100%), MSH3 (5/9, 56%), FBXW7 (5/9, 56%), and BRAF (5/9, 56%)." (PMID 30894686, 2019). "CircRNAs derived from oncogenic fusion genes, such as circMLL/AF9, can contribute to tumor-promoting properties, while circ-FBXW7, which is derived from a tumor-suppressive E3 ligase, can repress tumorigenesis." (PMID 31446897, 2019). "Inactivating mutations of FBXW7 have been found in a large spectrum of cancer types, including CRC, and its role as tumor suppressor is widely reported." (PMID 31569395, 2019). "Since these cell-cycle accelerators are known as oncoproteins that are frequently upregulated in a wide range of human cancers including CRC, FBXW7 has been initially considered a tumor suppressor." (PMID 31067777, 2019). "Here, we focus on FBXW7, a bona fide tumor suppressor that restrains EMT and directly target mTOR for ubiquitin degradation in NSCLC." (PMID 29633504, 2018). "Our studies focus on the views that FBXW7 executes its tumor suppressor function by inhibition of EMT and the mTOR/p70S6K pathway, ensuring the efficiency of EGFR‐TKI treatment in NSCLC." (PMID 29633504, 2018). "The majority of FBXW7 targets are known as proto-oncogenes, further supporting FBXW7’s role as a tumor suppressor." (PMID 30086763, 2018). "FBXW7 acts as a tumor suppressor involved in the ubiquitination and degradation by the proteasome of substrates with oncogenic activity, including MCL-1." (PMID 29805751, 2018). "Consistent with the in vitro data, downregulation of FBXW7 accelerated tumor formation at the implantation site and promoted gefitinib resistance in vivo." (PMID 29633504, 2018). "It is well known that FBXW7 is a tumor suppressor and its down-regulation was displayed in numerous human malignancies, including GC." (PMID 29720189, 2018). "Along these lines, because GSK3β-mediated phosphorylation is required for degradation of c-Myc, cyclin E and MCL1, any signaling pathway that affects GSK3β activity can have a profound impact on FBXW7’s ability to perform its tumor suppressor activities." (PMID 30086763, 2018). "FBXW7, a major tumor suppressor, negatively regulates more than a dozen of oncogenic proteins with pivotal roles in cell cycle progression, proliferation, and cell division." (PMID 29594129, 2018). "FBXW7 was reported to regulate tumor apoptosis, growth arrest and epithelial-to-mesenchymal transition in GC, and it also played an important role in drug resistance." (PMID 29720189, 2018). "Intriguing, in line with our study, miR-92a-3p was reported to promote tumor growth in multiple tumors by targeting FBXW7." (PMID 29720189, 2018). "HCC patients with high histological grade and advanced tumor-node-metastasis stage show lower FBXW7 protein expression." (PMID 30086763, 2018).
tumor (continued). "Functional studies revealed that upregulation of FBXW7-185aa in tumor cells inhibited cell proliferation and cell cycle progression, whereas knockdown of FBXW7-185aa promoted the malignant development of tumors." (PMID 30400981, 2018). "FBXW7 has been identified as a tumour-suppressor gene following studies showing its role in the ubiquitin-dependent degradation of a number of oncoproteins." (PMID 30001747, 2018). "Among them, deletions in 4q (FAT1 and FBXW7) and 2q (TRIP12) affect genes that are frequently mutated in some cancer types, suggesting a tumour suppressor role of these ones." (PMID 29416628, 2018). "While most studies focus on the cell-autonomous function of FBXW7 in tumor cells, it has also been shown that FBXW7 affects the tumor microenvironment and inhibits tumor metastasis." (PMID 30086763, 2018). "FBXW7 is a critical tumor suppressor and one of the most commonly deregulated ubiquitin-proteasome system proteins in human cancer." (PMID 30086763, 2018). "F-box and WD repeat domain-containing 7 (FBW7) is a well-established tumor suppressor in diverse mouse and human cancers." (PMID 28036276, 2017). "NOTCH1, CDKN2A, FBXW7, FAT1, and ZNF750 were considered as tumor suppressors and showed recurrent inactivating mutations." (PMID 29348864, 2017). "Increased c-Myc expression was accompanied by decreased Fbxw7 protein expression in tumor tissues from mouse and patients." (PMID 28422719, 2017). "FBXW7 (F-box and WD repeat domain-containing 7) is a tumor suppressor which is an E3-ubiquitin ligase involved in the ubiquitination of many growth related proteins." (PMID 28611316, 2017). "Fbxw7 acts as a tumor suppressor via inducing apoptosis and growth arrest in various kinds of tumors." (PMID 28422719, 2017). "FBXW7, on the other hand, is a well-established tumour suppressor that targets various oncogenic proteins for degradation." (PMID 28090088, 2017). "Recent studies have shown that FBXW7 is believed to be a tumor suppressor that targets various oncogenic proteins." (PMID 28149200, 2017). "FBXW7 is a tumor suppressor that regulates degradation of oncogene proteins such as MYC, cyclin E, Notch, and MCL1." (PMID 28464881, 2017). "FBXW7 is a key regulator of tumor malignant potential, and its substrate MCL1 regulates therapeutic resistance in human malignancies." (PMID 29348852, 2017). "Studies on FBXW7 as tumor suppressor are extremely important to understand tumorigenesis as it can act as a therapeutic target as well as a diagnostic marker in cancers." (PMID 28149200, 2017). "FBXW7, a well-established tumour-suppressor gene that targets various oncogenic proteins for degradation, was mutated in 7.4% (7/94) and deleted in 6.4% (6/94) of samples." (PMID 28548104, 2017). "As results, the tumor incidence was obviously higher in Fbxw7+/− mice (13/20) than in Fbxw7+/+ mice (6/20) after 35-week observation." (PMID 28422719, 2017). "Although FBXW7 appears to be associated with regulation of the degradation of multiple oncogenic proteins such as c-Myc, cyclin E, and c-Jun, our findings presented in this study may suggest a putative tumor-suppressive mechanism of FBXW7 involving negative regulation of hnRNPK stability." (PMID 28423622, 2017). "Through the past decade, E3 ligase FBXW7 has been reported to play critical roles in tumour initiation and progression, cell proliferation, differentiation and angiogenesis." (PMID 28287082, 2017). "Inhibition of miR-223-3p induced significant upregulation of Fbxw7, a tumor suppressor that has been previously reported to correlate with HCC prognosis and found to be consistently reduced in HCC tumors and cell lines." (PMID 28562643, 2017). "In the context of HCC, Fbxw7 has already been found to be significantly downregulated in tumors compared to normal liver, with both mRNA and protein expression correlating with tumor stage, histological grade and disease-free survival." (PMID 28562643, 2017).
tumor (continued). "FBXW7, which is regulated by miR-223, has been identified as a tumor suppressor gene in several cancers, and plays key roles in modulating the degradation of various onco-protein substrates, including c-Myc, cyclinE, Notch, c-Jun, mTOR, and MCL1." (PMID 28507201, 2017). "qRT-PCR showed that compared to adjacent non-tumor tissues, FBXW7 was significantly down regulated in tumor tissues, and also significantly decreased in metastatic compared to non-metastatic tissues." (PMID 28423622, 2017). "Many observations indicate that FBXW7 lies at the nexus of many pathways include controlling cell growth, cell differentiation, and tumor genesis." (PMID 27306418, 2016). "To explore the esophagus-specific functional relationships for Fbxw7, Stk40, and Pdcd4 (tumor-suppressor targets of miR-223, -31, -21), we employed FNTM for the rat." (PMID 26918602, 2016). "The FBXW7 protein expression was also confirmed by immunohistochemical analysis in vivo tumor tissues." (PMID 27306418, 2016). "As FBXW7 mediates the ubiquitin‐dependent proteolysis of several oncoproteins including c‐Myc, cyclin E1, c‐Jun, and Notch, FBXW7 is considered a tumor suppressor." (PMID 26832397, 2016). "Since this discovery in yeast, a wealth of experimental evidence, suggests that Fbxw7 is a tumor suppressor through negative regulation of many oncogenic proteins." (PMID 26886596, 2016). "The mRNA levels of Fbxw7 and Stk40 in all 3 ZD tumor groups were statistically significantly reduced as compared to ZST esophagus (**P < 0.01, ***P < 0.001)." (PMID 26918602, 2016). "Because many of the substrates that FBXW7 targets for degradation are well-known oncoproteins, such as Cyclin E, c-Myc, Aurora kinase A (AURKA) and Notch-1, FBXW7 is generally accepted as a tumor suppressor." (PMID 27409838, 2016). "FBXW7 is emerging as a major human tumor suppressor that lies at the nexus of several pathways that control cell growth, differentiation and tumorigenesis." (PMID 27376155, 2016). "Given the role of FBXW7 as a tumor suppressor gene we predicted that higher expression of these overlapping and FBXW7 positively correlated genes would have a good prognosis for patients." (PMID 26575021, 2015). "Network analyses showed significant enrichment of cell cycle related genes (p < 3.79E-02) consistent with the tumor suppressor functions of Fbxw7 in cellular growth and division pathways." (PMID 26575021, 2015). "Here we used gene transcript profiling to gain a deeper understanding of the role of FBXW7 in tumor development and to determine the influence of mTOR inhibition by rapamycin on tumor transcriptome and biological functions." (PMID 26575021, 2015). "FBXW7 is considered an haploinsufficient tumor suppressor that targets several proto-oncoproteins for degradation, including cyclin E, Myc, c-jun, Mcl1." (PMID 25885523, 2015). "FBXW7 primarily exerts its tumor suppressor activity by ubiquitinating different oncoproteins including mTOR." (PMID 26575021, 2015). "Taken together, our results reinforce the role of FBXW7 as a tumor suppressor and indicate that FBXW7 is a viable target for therapeutic intervention." (PMID 26575021, 2015). "Consistently, there is an inverse correlation between miR-27a expression and FBXW7 levels in human tumor samples." (PMID 25888377, 2015).
tumor (continued). "FBXW7 is considered a tumor suppressor that targets cytoproliferative proteins like cyclin E, c-Myc, and Aurora kinases." (PMID 26171402, 2015). "LOH at 4q28.1–35.2 was also frequent in SCs (50%); this region includes the loci of tumor suppressor FBXW7 (F-box and WD repeat domain containing 7) and FAT1 (FAT tumor suppressor homolog 1)." (PMID 26043110, 2015). "Tumor growth curves, generated over 21 days, revealed that Fbxw7 overexpression slowed down Hep3B tumor growth in mice." (PMID 24884509, 2014). "Fbxw7 has been characterized as a general tumor suppressor in human cancer and plays a critical role in cell cycle progression, apoptosis, tumor metastasis and drug resistance." (PMID 24884509, 2014). "FBXW7 was regulated by miR-223 and miR-27a and served as a tumor suppressor to inhibit tumor growth and progression." (PMID 25115392, 2014). "FBW7 (F-box and WD repeat domain-containing 7) or Fbxw7 is a tumor suppressor, which promotes the ubiquitination and subsequent degradation of numerous oncoproteins including Mcl-1, Cyclin E, Notch, c- Jun, and c-Myc." (PMID 24899581, 2014). "In this study, we have further confirmed that Fbxw7 suppresses tumor progression by promoting apoptosis and growth inhibition in HCC." (PMID 24884509, 2014). "In these 60 cases, Fbxw7 expression was detected in 43 (71.7%) of the normal tumor-adjacent tissues, whereas only 24 (40%) of the HCC specimens showed a positive Fbxw7 signal (P < 0.01)." (PMID 24884509, 2014). "As a general tumor suppressor, both Fbxw7 mRNA and protein expression levels have been shown to be down-regulated in various cancers." (PMID 24884509, 2014). "BrdU and MTT assays were performed to test the effect of altering Fbxw7 levels on tumor cell proliferation and viability, respectively." (PMID 24884509, 2014). "Restoring YAP expression partially restored tumor growth, for the Fbxw7-overexpressing Hep3B cells (P < 0.01)." (PMID 24884509, 2014). "The levels of selected Fbxw7 substrates were analysed in R482Q/+;1322T and 1322T tumours paired for size and location." (PMID 23676439, 2014). "Some F-box proteins, such as SKP2, display oncogenic function, while other proteins, such as FBXW7,act as tumor suppressors." (PMID 25115392, 2014). "The E3 ubiquitin ligase Fbxw7 functions as a general tumor suppressor by targeting several well-known oncoproteins for ubiquitination and proteasomal degradation." (PMID 24884509, 2014). "PIN1 is able to promote the degradation of c-Myc and cyclin E with the mediation of the FBXW7 E3 ligase, thus providing the evidence that it acts as a tumor suppressor." (PMID 24179535, 2013). "Overexpression of FAM83D in tumor cells leads to downregulation of FBXW7, resulting in elevated levels of numerous oncoproteins downstream of FBXW7." (PMID 24344117, 2013). "FBXW7 is a tumor suppressor that controls the protein levels of many well-known oncogenes and is frequently mutated in many cancers." (PMID 24344117, 2013). "FBXW7 acts as a tumor suppressor in numerous types of human cancers through ubiquitination of different oncoproteins including mTOR." (PMID 23454868, 2013). "However, how the mutation/loss of Fbxw7 results in tumor development remains largely unknown." (PMID 23454868, 2013). "FBXW7 is a known tumor suppressor but the presence of MUC1 in UPD region is surprising as it is a well-known oncogene." (PMID 24204606, 2013).